CD38 (CD38 molecule)
Diseases named in the same sentence as CD38 in open-access papers (continued):
Sharing a sentence is not in itself a finding about the gene and the disease.
tumor (continued). "Daratumumab is a human IgGκ monoclonal antibody targeting CD38 with a direct on-tumor and immunomodulatory mechanism of action." (PMID 33588922, 2021). "This bispecific Ab showed better anti-tumour effects compared to the SA-biotin system when administered to CD38+ tumour-bearing mice." (PMID 34727950, 2021). "We found that the expression of PD-1 significantly increased in tumor-infiltrating CD38+ CD8+ T cells compared with adjacent normal tissues and peripheral blood." (PMID 33934206, 2021). "The immunosuppressive role of CD38 served as the escape mechanism for tumour cells from PD-1/PD-l1 blockade whereby it inhibited CD8+ T-cell activity through the adenosine receptor signalling pathway." (PMID 34572431, 2021). "CD38 contributes to the regulation of antitumor immunity and can be used as a prognostic biomarker and potential immunotherapeutic target, which suggests a potential application of CD38 as a tumor marker." (PMID 33820568, 2021). "CD38 expression expressed on Tregs and MDSCs is infiltrated in the tumor microenvironment and stimulated adenosine production via the CD38–CD203a-CD73 axis, and therefore inhibits CTL function." (PMID 33562324, 2021). "Immuno-PET imaging of disseminated MMs using the 68Ga-anti-CD38 nanobody delineated bone lesions as early as 3–4 weeks after tumor cell inoculation in mice." (PMID 33925941, 2021). "The immunomodulatory actions of daratumumab minimize the immune-suppressive functions of CD38+ myeloid-derived tumor suppressor cells, regulatory T cells, and regulatory B cells and increase T-cell clonality." (PMID 32001798, 2020). "The ability of CD38-specific hcAbs to induce antibody-dependent cellular cytotoxicity (ADCC) was tested with luciferase-expressing tumor cell lines LP-1, Daudi, and CA46 as targets and CD16-transduced NK-92 cells or primary NK cells as effector cells." (PMID 32194826, 2020). "CD38-targeted nanoparticles showed significantly greater tumor cell uptake and enhanced efficacy over CD138-targeted nanoparticles in vivo that would not have been expected from solely the results of the in vitro study." (PMID 33138841, 2020). "We further performed IHC staining from paraffin-embedded tumor tissue sections from LLC1 hind-leg tumors grown on WT mice for CD38 and CD203a protein expression." (PMID 33194619, 2020). "In contrast, tumor tissues with high lymph node stage showed more CD8+CD38+ co-expression than at low lymph node stage." (PMID 32050977, 2020). "In conclusion, our in vivo data show that anti-CD38 and anti-PD-1 antibodies synergize to eradicate CD38-expressing tumor cells." (PMID 33321969, 2020). "In NSG mice models with implanted CD38-expressing Burkitt's lymphoma tumor cells and previously unstimulated human PBMCs, BsAb treatment inhibited tumor growth and prolonged survival." (PMID 32391000, 2020). "Daratumumab and other CD38-specific antibodies mediate killing of tumor cells by natural killer cells, macrophages, and the complement system." (PMID 33396591, 2020). "We compared the capacity of these CD38-specific hcAbs and daratumumab to induce CDC and ADCC in CD38-expressing tumor cell lines in vitro and in patient MM cells ex vivo as well as effects on xenograft tumor growth and survival in vivo." (PMID 32194826, 2020). "Treatment with an anti-CD38 antibody or genetic deletion of CD38 were shown to inhibit mitochondrial transfer from BMSCs to MM cells and induce tumor shrinkage in xenografts models." (PMID 32635428, 2020). "In contrast, treatment with CD38-specific hcAbs or with daratumumab resulted in significant inhibition of tumor cell growth as compared with isotype control treatment from day 28 (all p<0.001, as compared with isotype control treatment from day 28)." (PMID 32194826, 2020). "One such MM-specific model targets CD38 on the tumor cell, and stimulates both CD3 and CD28 on the T cell." (PMID 32391000, 2020).
tumor (continued). "Recently, Chen et al12 demonstrated that CD38 upregulation in tumor induces resistance to programmed cell death 1 (PD‐1)/programmed cell death ligand 1 (PD‐L1) blocking antibodies and coinhibition of CD38 and PD‐L1 improves antitumor immune responses." (PMID 31991058, 2020). "In fact, these mechanisms show a primary dependence on the density of the CD38 molecules expressed by the target tumor." (PMID 33322499, 2020). "The CD38-NAD+ signaling pathway seems to have a relevant role in the formation of a suppressive tumor microenvironment and promotes the activity of inhibitory cell types, such as MDSCs, Tregs, Bregs and certain subtypes of NK cells." (PMID 32225002, 2020). "Myeloablation induced by CD123 CAR T-cells and fratricide killing of CD38 CAR T-cells are more thorny off-tumor toxicities than B-cell aplasia that impede their development." (PMID 33643279, 2020). "Increased mitochondrial bioenergetics and ATP production in MM is also associated with mitochondria transfer from BMSC via tumor-derived TNT, and tumor cell CD38 supports the formation of TNT." (PMID 31991829, 2020). "The mechanism of action of daratumumab is based on the elimination of tumor cells expressing high levels of CD38 through antibody-dependent cellular cytotoxicity and complement-dependent cytotoxicity." (PMID 31963337, 2020). "Combination therapies (i.e., anti-CD38 MoAbs plus IMiDs and/or proteasome inhibitors) are needed to lessen the tumor burden in MM, and the rate of relapses justifies an escalation approach to improve patient survival." (PMID 32531894, 2020). "The mechanisms of resistance to ICIs are quite different, and among them the up-regulation of CD38 by tumor cells determines a functional impairment of CD8 T cells, with a consequent tumor immune escape." (PMID 33123122, 2020). "CD38 cytotoxic antibodies can, therefore, exhibit direct on-tumor activity as well as indirect immunomodulatory anti-tumoral effects." (PMID 32225002, 2020). "Conversely, all three CD38-specific hcAbs effectively induced ADCC of tumor cell lines and primary MM cells with comparable potency to daratumumab." (PMID 32194826, 2020). "There is evidence that tumor-derived signals directly influence the level of CD38 expression on MDSCs, thus contributing directly to immune escape." (PMID 32225002, 2020). "A different mechanism of CD38 regulation was also recently reported, which operates through the action of the tumor suppressor miR-26a." (PMID 33096610, 2020). "The goal of our study was to establish assays for monitoring the enzymatic activities of CD38 on the cell surface of tumor cells and to assess the effects of CD38-specific antibodies on these activities." (PMID 33396591, 2020). "Although the anti-tumor activity mechanism is still under investigation, there is evidence that anti-CD38 mAbs can kill CD38-overexpressing cancer cells by multiple processes." (PMID 33329591, 2020). "Of these, Fc-dependent natural killer cell-mediated ADCC is a key mechanism that occurs in both low and high CD38-expressing tumor plasma cells." (PMID 32409691, 2020). "CXCL12/CXCR4 axis synergizes with CD38 to support migration as a central step in tumor disease progression." (PMID 33123122, 2020). "In vivo, CD38-specific heavy chain antibodies significantly reduced the growth of systemic lymphomas and prolonged survival of tumor bearing SCID mice." (PMID 32194826, 2020). "To this end, we adapted the fluorometric cGDPR assay as well as a high-pressure liquid chromatography (HPLC) assay to monitor the enzyme activities of living tumor cells expressing CD38." (PMID 33396591, 2020). "In an in vivo follow up, the BsAb construct with the most prolonged anti-tumor activity and best T cell stimulation was the one with a balanced CD38 and CD3 affinity." (PMID 32391000, 2020).
tumor (continued). "This is supported by the recent studies showing that expression of CD38 facilitates T cell exhaustion at the tumor site, which is refractory to restore their functionality by immune checkpoint blockade therapy." (PMID 32709019, 2020). "In ADCP, effector cells (such as monocytes and macrophages) bind to the Fc tail of the CD38 antibody via their FcγR, leading to opsonization of the target (i.e., tumor) cell." (PMID 32331242, 2020). "Immune checkpoint inhibitors combined with adenosine receptor antagonists can relieve the inhibitory effect of CD38 on tumor cells on CD8+ T-cell function." (PMID 32850400, 2020). "Addition of araF-NAD effectively abrogates the increase of cGDPR, indicating that this is largely due to CD38 expression on the surface of the tumor cells (red curves)." (PMID 33396591, 2020). "We monitored the enzymatic activity of CD38-expressing MM and other tumor cell lines, using fluorometric and HPLC assays." (PMID 33396591, 2020). "The goal of our study was to establish appropriate assays for monitoring the different enzymatic activities of CD38 on the cell surface of tumor cells, and to assess the effects of CD38-specific antibodies on these activities." (PMID 33396591, 2020). "This analysis showed that CD38 was significantly correlated with tumor purity, CD8+ T cells, CD4+ T cells, and B cells in EOC." (PMID 32425977, 2020). "Tumor antigen specific CD8 T cells in dLNs, however, showed a very low frequency of CD8 T cells associated with a terminally exhausted phenotype (CD38+CD101+ TCF1lo)." (PMID 32391270, 2020). "In a direct in vitro comparison between daratumumab, MOR202 (surrogate) and isatuximab (surrogate) tested on CD38-expressing Daudi tumor cells, daratumumab was most effective in inducing CDC, followed by MOR." (PMID 32331242, 2020). "We further assessed the anti-tumor immune response following treatment with anti-mouse CD38 as a single agent or in combination with an anti-PD-1 antibody in immunocompetent mouse tumor models." (PMID 33321969, 2020). "Analysis of CD38 expression of MM cells from PB overlaps that of MM cells from BM in terms of CD38dim/- expression and rapid decrease of circulating tumor cells after the first Dara infusion." (PMID 31936617, 2020). "Because non-tumor cells also express CD38, it would be beneficial for cancer therapy if Nb-CAR-NK cells would preferentially deplete CD38high cells." (PMID 32013131, 2020). "The ability of CD38-specific hcAbs to inhibit tumor growth in vivo was tested in mouse xenograft experiments after systemic administration of CA46-luc cells." (PMID 32194826, 2020). "We demonstrate the immunomodulatory effects of an anti-CD38 antibody in vivo (a decrease in immune suppressor cells) and show that targeting two pathways, CD38 and PD-1, can result in enhanced anti-tumor effects vs. either pathway alone." (PMID 33321969, 2020). "Blocking PD-1/PD-L1 increased all-trans retinoic acid (ATRA) and type I IFN in the treatment-sensitive TME, which leads to activation of the retinoic acid receptor alpha (RAR-α) and subsequently CD38 expression on tumor cells." (PMID 32380703, 2020). "Treatment of CD38-expressing tumor cells with DTT, indeed, resulted in a dose-dependent inhibition of the conversion of NAD+ to both, ADPR and cADPR." (PMID 33396591, 2020). "Daratumumab was shown to induce ADCC against several different CD38-expressing tumor cell lines, patient MM cells, as well as plasma cell leukemia cells." (PMID 32331242, 2020). "To analyze the enzymatic reactions catalyzed by CD38-expressing tumor cells, we adapted an HPLC assay to measure the concentrations of NAD+, ADPR, and cADPR, after incubation of cells with NAD+ or cADPR." (PMID 33396591, 2020). "Isatuximab induces both Fc-dependent and Fc-independent pathways to kill CD38-expressing tumor cells." (PMID 32409691, 2020).
tumor (continued). "Daratumumab is the first of several anti-CD38 monoclonal antibody-based therapeutics that improve anti-tumor immunity and also demonstrate an inhibitory effect on AML mitochondrial transfer in vitro and in vivo." (PMID 33365311, 2020). "In 2019, Zhang and his team found that CD38/CD101 co-repression on tumor-infiltrating lymphocytes were related with a poor survival in PDAC patients." (PMID 33062410, 2020). "Although all CD38-targeted nanoparticles showed similar accumulation at the tumor site, tumor cell uptake increased with peptide density up to 0.5% CD38 and then sharply decreased at 1%." (PMID 33138841, 2020). "In Kaplan–Meier plotter databases, except the microarray analysis of CD38 expression, RNA sequencing data were also acquired and used for online analysis of the prognostic value of CD38 in 373 patients of EOC with diverse tumor mutation statuses." (PMID 32425977, 2020). "CD38 was correlated with tumor-infiltrating lymphocytes (TILs), especially with activated CD8+ T cells." (PMID 32425977, 2020). "Obvious off-tumor effects have been found due to CD38 expression in normal cells, especially in CAR T-cells, resulting in fratricide and short-term survival." (PMID 33643279, 2020). "A number of studies have investigated the mechanism of action of isatuximab, identifying both fragment crystallizable (Fc)-dependent and Fc-independent activities leading to killing of CD38-expressing tumor cells." (PMID 32922390, 2020). "Taken together, the results indicate that isatuximab has preferential cytotoxic effect toward high CD38-expressing tumor cells but spares low CD38-expressing cells in normal tissues." (PMID 32922390, 2020). "Daratumumab is a human immunoglobulin Gκ monoclonal antibody targeting CD38 with a direct on-tumor and immunomodulatory mechanism of action." (PMID 32001798, 2020). "Mitochondrial trafficking was prevented by a blocking antibody against or knockdown of the surface molecule CD38, which also reduced tumor burden and improved animal survival." (PMID 33365311, 2020). "CD38 on tumor cells then converts tumor microenvironmental NAD+ to immunosuppressive adenosine via the CD38/CD203a/CD73 pathway." (PMID 32380703, 2020). "It not only exploits classical ADCC mechanisms depending on CD38 expression on tumor cells, but also plays a multifaceted immuno-modulatory role (recently reported in MM patients)." (PMID 33292550, 2020). "The CD38-targeted nanoparticles displayed a much improved biodistribution profile than free doxorubicin by improving drug accumulation at the tumor site while reducing its accumulation at major organs." (PMID 33138841, 2020). "CD38 and other enzymes on the surface of cancer cells hydrolyze these nucleotides to immunosuppressive mediators, thereby hampering anti-tumor immune responses." (PMID 33396591, 2020). "Nonetheless, it is evident that the tumors grew substantially faster than those in the CD38-S3I-NP group (tumor volume at 288 h was 16.8 times higher)." (PMID 30791634, 2019). "This potential of on-target, off-tumor toxicity can be a stumbling block to clinical implementation of CD38-directed CAR-T cell therapies." (PMID 31379824, 2019). "The number of HLA-DR and CD38-coexpressing CD8+ T cells can be up to five times higher within the tumor compared to the peripheral blood of cancer patients." (PMID 31861847, 2019). "In HCC, CD38+ is found to be expressed both on immune infiltrates within the TME as well as on the HCC tumor cells." (PMID 31861847, 2019). "In esophageal cancer, CD38 was found to be upregulated on myeloid-derived suppressor cells (MDSCs), occurring through the accumulation of tumor-derived secreted factors including IL-6, IGFBP3, and CXCL16." (PMID 31878283, 2019). "IHC staining of FFPE tumor sections revealed the expression of CD38 by cells residing in the liver sinusoids." (PMID 31552039, 2019).
tumor (continued). "Because single agent CD38 blockade had a marginal effect on tumor growth, the treatment with anti-PD(L)-1—either first or in combination—is likely necessary for an optimal immune response." (PMID 31878283, 2019). "In view of this, the expression of CD38 on tumor-infiltrating macrophages in the present study raises the possibility of participation in this mode of immunosuppression." (PMID 31552039, 2019). "Biopsies show unique aggregations of CD38+ tumor infiltrating lymphocytes (TILs) in HCC, and the presence of larger numbers of CD38+ TILs is associated with improved effectiveness of immunotherapy in HCC." (PMID 31861847, 2019). "CD38 is a valuable target for therapeutic mAbs because of (i) its ability to impair tumor growth either by directly targeting cells or by inducing immune modulation." (PMID 31068926, 2019). "In Burkitt-like lymphoma with the 11q aberration, the expression patterns of LMO2, CD38, and c-Myc in the tumor cells were similar to those in BL tumor cells." (PMID 31484540, 2019). "First, during daratumumab treatment it has been reported a rapid decrease in CD38 expression levels not only on tumor (e.g., MM) cell surfaces, but also in normal B, T and NK cells." (PMID 31783629, 2019). "Daratumumab and TAK-079 lack the ability to directly induce MM cell death; however, FcγR-mediated cross-linking of daratumumab induces programmed cell death of CD38-positive MM tumor cell lines." (PMID 31779273, 2019). "While CD38 expression on cells within the TME, such as T cells, myeloid cells or macrophages, still exists as the prime focus of these research efforts, more data is beginning to accumulate regarding the influence of CD38 expression on the tumor cells." (PMID 31878283, 2019). "As CAFs and angiogenesis encourage tumor growth and metastasis, the anti-tumor effect of CD38 suppression can be explained by the removal of tumor-supporting elements in the TME." (PMID 31861847, 2019). "More relevant to time of day, some inflammatory mediators (Myd88, Cd4, Tlr9, Cd38, C3, Ly96) demonstrated nyctohemeral (day versus night) differences in control brain tissues that were abolished in tumor-bearing and/or tumor-resected mice." (PMID 31019214, 2019). "In a xenograft mouse model, CD38-S3I-NP significantly reduced the tumor size by 4-fold compared to S3I-NP on day 12 after drug administration (p = 0.006)." (PMID 30791634, 2019). "We then assessed if the differences in tumor growth and survival between the CD38-S3I-NP and S3I-NP groups correlates with a difference in STAT3 down-regulation." (PMID 30791634, 2019). "The impact of CD38 expression within a heterogeneous solid tumor microenvironment, and specifically its expression on the tumor cells, remains understudied." (PMID 31878283, 2019). "Further substantiating the soundness of CD38-blockade as a cancer treatment, immunocompetent CD38-null mice display reduced tumor growth whereas tumors devoid of this ectonucleotidase grow slower both in immuno-competent as well as in immuno-deficient mice." (PMID 31244820, 2019). "Gathering knowledge such as this will allow for intelligent targeting of CD38, the reinvigoration of immune functionality and, ultimately, tumor elimination." (PMID 31878283, 2019). "Tumors (Cd4, tendency in Myd88, p = 0.07) and tumor resection (Myd88, Cd4, Tlr9, Cd38) eliminated these time-of-day differences by reducing light-phase gene expression relative to controls and or increasing dark phase expression." (PMID 31019214, 2019). "Both the VEGFR and anti-CD38 targeted immunotoxins were shown to compromise antigen-specific tumor cells in vitro, an effect that was also observed in vivo using CD7-targeted immunotoxins." (PMID 31695800, 2019).